INS (insulin)
Diseases named in the same sentence as INS in open-access papers (continued):
Sharing a sentence is not in itself a finding about the gene and the disease.
Insulin resistance (continued). "The relationship between GLP-1 and insulin appears to be bidirectional, as insulin stimulates GLP-1 secretion from the enteroendocrine cells and insulin resistance, in vitro and in vivo, is associated with impaired GLP-1 secretion." (PMID 32075958, 2020). "Aβ was used to induce neuronal insulin resistance in vitro and insulin was administered to stimulate insulin signaling." (PMID 32581820, 2020). "It is important to note that apoA-I stimulates insulin secretion by beta cells and enhances insulin-dependent and insulin-independent glucose uptake and so improves glycemic control and attenuate insulin resistance of T2D patients." (PMID 32517119, 2020). "Primary outcomes: Fasting glucose, fasting insulin, homeostasis model assessment of insulin resistance, glycosylated hemoglobin." (PMID 33019401, 2020). "This was accompanied by a significant increase in insulin resistance and reduction in insulin sensitivity, as measured by the HOMA-IR and Matsuda index, respectively, at 6 and 12 months." (PMID 33315154, 2020). "Insulin resistance decreases the ability of insulin to inhibit hepatic gluconeogenesis, a key step in the development of metabolic syndrome." (PMID 33348802, 2020). "At the same time, short-sleepers were characterized by the higher values of insulin and insulin resistance assessed by the homeostatic model assessment for insulin resistance (HOMA-IR)." (PMID 32630105, 2020). "Defects of normal insulin function significantly contribute to the onset of hepatic insulin resistance and T2D." (PMID 33038072, 2020). "However, in the overweight/obese individuals with insulin resistance, decreased insulin sensitivity was strongly associated with reduced CVR even after adjusting for BMI, suggesting that the metabolic consequences, and not obesity itself, may be driving the adverse effects on CVR." (PMID 32082607, 2020). "The aim of this cross-sectional study was to determine the relation between microbiota composition and tissue-specific insulin-sensitivity in two independent cohorts of obese males with ranging levels of insulin resistance." (PMID 32371932, 2020). "This ketosis type has characteristics of high blood BHBA (but lower than type I ketosis), NEFA, and insulin (INS) concentrations with hyperglycemia that shows insulin resistance (IR), and mainly occurs at 1 to 2 weeks postpartum." (PMID 32054179, 2020). "Fatty liver occurs from simple steatosis with accumulated hepatic lipids and hepatic insulin resistance to severe steatohepatitis, with aggravated lipid accumulation and systemic insulin resistance, but this progression is still poorly understood." (PMID 32532003, 2020). "Reduced level of adiponectin and increased levels of interleukin-6 (IL-6), tumor necrosis factor-α (TNF-α), free fatty acids, and resistin can reduce insulin-mediated glucose uptake due to insulin resistance." (PMID 32047529, 2020). "Prior studies have reported a close relationship between insulin resistance and urinary uric acid clearance, and that insulin sensitivity (assessed by euglycaemic clamp) is a strong predictor of serum urate levels." (PMID 33148335, 2020). "The addition of 300 or 400 μM PA for 12 h was shown to induce insulin resistance and impair insulin-stimulated glucose uptake." (PMID 33362555, 2020). "T2DM is characterized by both insulin resistance (reduced insulin sensitivity of insulin target tissues as a consequence of obesity) and β-cell failure (insulin insufficiency), leading to hyperglycemia." (PMID 32604774, 2020). "The need to secrete increasing amounts of insulin to compensate for progressive insulin resistance and the hyperglycemia-induced oxidative stress lead to an eventual deterioration of pancreatic β-cells." (PMID 33007997, 2020). "For example, IRS-1 regulates insulin action in skeletal muscle as evidenced by findings that genetic ablation of IRS-1 results in insulin resistance and hypertriglyceridemia." (PMID 32610588, 2020).
Insulin resistance (continued). "The direct effect of insulin on mitochondrial function is attenuated in insulin resistance subjects and HFD fed animals." (PMID 32987623, 2020). "SIRT1 is also an important regulator of insulin sensitivity, as systemic knockout of Sirt1 leads to insulin resistance." (PMID 33321755, 2020). "Various studies using AD animal models have shown that diet‐induced insulin resistance/chemically induced insulin signaling impairment increases AD pathology." (PMID 32170854, 2020). "Insulin resistance (IR) refers to a pathological status in which there is decreased biological regulation of insulin." (PMID 33133211, 2020). "Excessive ROS have been linked to activation of pro-inflammatory molecules, which can disrupt the insulin signaling and contribute to insulin resistance." (PMID 32922365, 2020). "The main reasons for T2DM are impaired tissue insulin sensitivity and insulin resistance which was coupled to pancreatic β-cell dysfunction." (PMID 32655759, 2020). "In the present study, we examined the effect of RSV on high insulin (HI)-induced insulin resistance in skeletal muscle cells in vitro and investigated the mechanisms involved." (PMID 32230718, 2020). "In conclusion, the impaired insulin signaling in the gastrocnemius muscles represented an alternative mechanism for the induction of postischemic hyperglycemia and insulin resistance, with propranolol improving the impairment." (PMID 32492962, 2020). "Human clinical trials found improvements in measurements of glucose, insulin, insulin resistance, and blood lipids, and markers of inflammation." (PMID 32341338, 2020). "Pro-inflammatory cytokines are key actors of the disruption of insulin signaling leading to insulin resistance." (PMID 32140136, 2020). "The elevated valine levels in the GDM group can thus contribute to decreased insulin signaling and worsen insulin resistance." (PMID 33105558, 2020). "In the present study, both T2DM models exhibited a phenotype of insulin resistance that was characterized by impaired insulin tolerance or glucose tolerance and reduced Akt phosphorylation." (PMID 32194828, 2020). "Aging of mice is accompanied by increased peripheral insulin resistance as well as augmented insulin secretion 48, implying that beta-cell compensation is necessary to maintain euglycemia in aged mice." (PMID 32641996, 2020). "After an eight-week intervention, body mass index (BMI), waist circumference (WC), fasting glucose, fasting insulin, and homeostatic model assessment for insulin resistance (HOMA-IR) were significantly reduced." (PMID 32466456, 2020). "In a group of 26 subjects varying in insulin sensitivity, insulin resistance was negatively correlated with adipose tissue LPL activity." (PMID 32504883, 2020). "Increased activation of muscle mTOR by nutrient overload was shown to lead to increased serine phosphorylation of IRS-1, impaired insulin signaling, and induction of insulin resistance." (PMID 32664532, 2020). "Here, we investigated the effect of hydralazine on insulin resistance by evaluating the serum levels of glucose and insulin in SHRs." (PMID 33315911, 2020). "Reduced adipose tissue IRS-1 expression was reported in obese subjects, which impairs the downstream insulin signaling and the development of insulin resistance accompanied by increased adiposity." (PMID 32937828, 2020). "Obesity leads to the progression of insulin resistance and type II diabetes mellitus, and studies have reported that insulin signaling pathways regulate adiposity cell differentiation." (PMID 32168898, 2020). "Numerous studies have established that serine phosphorylation of IRS-1 leads to impaired insulin action and contributes towards insulin resistance." (PMID 32230718, 2020). "In contrast, markers of insulin-resistance were positively correlated only in girls (fasting insulin levels (r: 0.56, p = 0.002), HOMA-IR (r: 0.52, p = 0.004)), but not in boys (fasting insulin levels (r: 0.11, p = 0.51), HOMA-IR (r: 0.06, p = 0.74))." (PMID 32987856, 2020).
Insulin resistance (continued). "The simultaneous increase in insulin production and improved insulin sensitivity is unprecedented and suggests a novel mechanism beyond insulin resistance for enhancing β‐cell insulin secretion." (PMID 33113267, 2020). "Insulin levels and homeostatic model assessment of insulin resistance (HOMA-IR) decreased after 12 months of intervention." (PMID 32967728, 2020). "The forthcoming consequence of the insulin resistance is hyperinsulinemia, which stems in part from excess release of insulin in the pancreas to compensate for insulin resistance." (PMID 32992734, 2020). "Adaptation of insulin-producing pancreatic β cells is critical for a proper response to pregnancy-related insulin resistance and includes increased β cell number, size, and insulin secretion." (PMID 32252821, 2020). "The use of HOMA-IR limits the interpretation of insulin resistance to the relationship between insulin and glucose at basal concentrations but has been shown to correlate well with the EHC." (PMID 32314253, 2020). "Insulin resistance was evaluated using homeostasis model assessment-insulin resistance, quantitative Insulin Sensitivity Check Index, fasting glucose/insulin ratio, Matsuda index, and total insulin levels during oral glucose tolerance test." (PMID 32431137, 2020). "Expression levels of the glucose transporter type 4 (GLUT4), responsible for insulin-mediated glucose uptake, has been reported to be reduced in both, rodents and human with insulin resistance." (PMID 32781523, 2020). "There was a decrease in body weight (BW), body mass index (BMI), waist circumference (WC), % body fat (%BF), fasting glucose, insulin levels, and insulin resistance (IR), by HOMA-IR, in the TG." (PMID 33037261, 2020). "Recent findings indicate that flaxseed lignans alleviate hepatic steatosis and insulin resistance by enhancing insulin signalling and AMP-activated protein kinase (AMPK) activation." (PMID 32252239, 2020). "Mice transfected with extra copies of the insulin gene generating 2–4-fold increase in insulin levels exhibited hyperglycemia, hypertriglyceridemia and insulin resistance." (PMID 32230718, 2020). "Nebivolol improved the insulin resistance-related variables (fasting glucose, fasting insulin, and HOMA-IR) while carvedilol was neutral." (PMID 32990863, 2020). "Insulin secretion is more markedly increased in obese men, as a way to compensate for a higher level of insulin resistance." (PMID 31754750, 2020). "Magnesium supplementation enhanced insulin sensitivity and decreased insulin resistance in diabetic rats mainly through increasing insulin receptor expression, affinity, and augmenting insulin receptor signaling." (PMID 32952944, 2020). "Myocardial insulin resistance contributes to heart failure in response to pathological stresses, therefore, a therapeutic strategy to maintain cardiac insulin pathways requires further investigation." (PMID 32223896, 2020). "These cytokines activate inflammatory pathways within adipocytes via paracrine mechanisms, such as JNK and IKKβ, which inhibit insulin signaling and lead to local insulin resistance." (PMID 33390968, 2020). "Previous studies have shown mild uncoupling is an antioxidant factor, that loss of UCP3 is associated with insulin resistance, and that the restoration of UCP3 protein content improves insulin sensitivity." (PMID 32760285, 2020). "Through the upregulation of sirtuin 1, RSV represses NF-κB pro-inflammatory responses in adipocytes and macrophages that infiltrate adipose tissue, leading to an improvement in insulin signaling and insulin resistance." (PMID 32102233, 2020). "ENPP1 is known to be involved in insulin resistance by inhibiting the interaction between insulin and the receptor at the level of the alpha subunit, resulting in decreased downstream insulin signaling activation." (PMID 32884006, 2020).
Insulin resistance (continued). "At the onset, pancreatic cells compensated for increased glucose levels by doubling insulin secretion (detectable within 2 weeks), but insulin secretion became significantly impaired as insulin resistance developed and β-cell mass continued to increase." (PMID 33261000, 2020). "Insulin resistance, in turn, produces higher levels of blood insulin as the body continues to secrete insulin in an attempt to maintain homeostasis in a malfunctioning negative feedback loop." (PMID 32742493, 2020). "Icariin, a major bioactive component extracted from plants of the Epimedium genus, has been shown to ameliorate insulin resistance in skeletal muscle cells and restore impaired hypothalamic insulin signaling in the rats with chronic unpredictable mild stress." (PMID 32581820, 2020). "Different factors can trigger a preexisting condition of insulin resistance or increase insulin requirements in a previously normoglycemic patient." (PMID 31876135, 2020). "Serum insulin levels and insulin resistance of CTFV-administered obese mice were lower than those of the DIO group." (PMID 33273564, 2020). "In normal pregnancy, insulin resistance increases in the second trimester, but most women remain euglycemic due to beta cell compensation and increased insulin secretion." (PMID 32785102, 2020). "Dysglycemia and type 2 diabetes results when islet β cells fail to maintain appropriate insulin secretion in the face of insulin resistance." (PMID 33353164, 2020). "In cultured adipocytes, hypoxia inhibits insulin-induced pathways and induces insulin resistance through an HIF-1-dependent mechanism." (PMID 33324235, 2020). "The 30%-T or 5%-L mice had lower plasma glucose, insulin, glucose area under the curve (AUC), homeostatic model assessment of insulin resistance (HOMA-IR), alanine transaminase, triglyceride, and tumor necrosis factor alpha levels." (PMID 32425738, 2020). "Intranasal insulin administration has been suggested as a clinically relevant approach to overcome brain insulin resistance and improve cognitive functions." (PMID 31929603, 2020). "In order to compensate, the islets of Langerhans in the pancreas elevate insulin levels in the blood (i.e., hyperinsulinemia) to overcome insulin resistance." (PMID 32612981, 2020). "Intranasal insulin administration has been suggested as a potential approach to overcoming brain insulin resistance and improving cognitive functions." (PMID 31929603, 2020). "Guinea pigs infected with Mtb developed non-diabetic hyperglycemia (untreated vs. uninfected p = 0.0002) and systemic insulin resistance as determined by glucose and insulin tolerance testing, respectively (untreated vs. uninfected p < 0.0001)." (PMID 33004826, 2020). "GDM develops when beta cell insulin secretion is unable to compensate for pregnancy-induced insulin resistance, and/or in conjunction with an impaired beta cell function." (PMID 33335512, 2020). "Increased insulin secretion, which occurs in the early phase of insulin resistance, promotes tumor growth per se." (PMID 33202621, 2020). "East Asians, including Japanese, have been reported to have a lower capacity for insulin secretion and lower insulin resistance compared to Caucasians." (PMID 32630741, 2020). "In conclusion, fresh PGJ lowers melatonin, increases the level of insulin, and ameliorates insulin resistance in people with IFG." (PMID 31993180, 2020). "As increased adiposity contributes to insulin resistance, insulin sensitivity was evaluated during the 25-week protocol and as expected the HFS diet induced a decreased sensitivity." (PMID 32012987, 2020). "Deregulation of lipid metabolism and insulin function in muscle and adipose tissue are hallmarks of systemic insulin resistance, which can progress to type 2 diabetes." (PMID 32041341, 2020).
Insulin resistance (continued). "Heterozygous PPARγ-null mice exhibited greater insulin sensitivity than wild-type littermates and were protected from the development of insulin resistance and glucose intolerance mediated by a HFD." (PMID 33348802, 2020). "While some research findings suggest that insulin resistance is induced by progesterone, others suggest that this is likely estrogen-related, and that progesterone only affects the half-life of insulin." (PMID 32215823, 2020). "Although LADA has distinct pathophysiological mechanisms of disease comparing to T1DM (less pronounced insulinopenia and significant insulin resistance), with the progression of the disease most patients eventually need insulin therapy." (PMID 33292447, 2020). "HmlΔ >/UAS-hid larvae with reduced Hml+ immune cells demonstrated a similar growth defect, reduced insulin signaling, elevated fat body inflammation, and hyperglycemia, all of which are characteristic signs of insulin resistance." (PMID 32849518, 2020). "Overall, our study finds that insulin resistance is one factor that contributes to the worse prognosis in breast cancer between Black and White women, potentially through direct effects of insulin on the tumor IR." (PMID 32393319, 2020). "The additional low dose of STZ injection led to mild impairment in insulin secretion, closely resembling the key characteristics of insulin resistance and pancreatic β-cell dysfunction in human T2D." (PMID 33716721, 2020). "Obesity and insulin-resistance initially results in high fasting insulin; this high level of insulin is thought to be due to beta-cell compensation in the face of progressive insulin-resistance, resulting in hyperinsulinemia with normal glucose tolerance." (PMID 32153503, 2020). "Meta-inflammation in combination with changes in fatty acid flux has been proposed to antagonise insulin signaling leading to insulin resistance." (PMID 31992650, 2020). "Insulin treatment of type 2 diabetes seems only warranted if hyperinsulinemia and concomitant (selective) insulin resistance can be avoided." (PMID 32819363, 2020). "Cells in which insulin accumulated demonstrated signs of insulin resistance and reduced levels of insulin receptors." (PMID 32326589, 2020). "The consumption of polyphenols has been shown to possess anti-diabetic properties by preventing insulin resistance or insulin secretion through different signaling pathways, this effect is associated with their capacity to exert genomic modulations." (PMID 32258479, 2020). "Brothers of PCOS women show elevated levels of total cholesterol, LDL, TG and insulin as well as insulin resistance." (PMID 32256454, 2020). "Postprandial responses of insulin in overweight subjects indicated insulin resistance in them though they had fasting and postprandial blood sugar levels similar to the NC group." (PMID 31941993, 2020). "Glucose intolerance and insulin resistance are the major pathologies found in the patients of metabolic disorders, which were evaluated by plasma glucose and insulin levels, and GTT and ITT assays." (PMID 32781739, 2020). "P2Y2 receptor, through the induction of the c-Jun N-terminal kinase (JNK) and prevention of insulin signaling, can promote insulin resistance in hepatocytes in T2DM." (PMID 32793223, 2020). "TF were more insulin resistant than CM, with a lower inverse of fasting insulin (P = 0.011) and a higher HOMA-IR (P = 0.012)." (PMID 31544944, 2020). "A significant influence of the “experimentalgroup” on the insulin sensitivity in females was shown:the index of insulin resistance, glucose and insulin levels in GE females were higher than in SHAM females, and exogenousestradiol normalized these indicators." (PMID 33659826, 2020). "While moderate hyperglycemia, e.g., originating from insulin resistance, induced an increase in β-cell mass and insulin secretion, marked hyperglycemia produced β-cell mass reduction due to glucose-induced acceleration of β-cell death." (PMID 33324238, 2020).